RNU6-672P (RNA, U6 small nuclear 672, pseudogene)
Gene: Small nuclear RNA gene on chromosome 11 (72,869,544 to 72,869,650, reverse strand). Ensembl gene ENSG00000206638.
Homologues: Orthologues: chimpanzee U6 (99% identical), guinea pig U6 (77% identical). Paralogues in human: RNU6-1060P (93% identical), RNU6-116P (92% identical), RNU6-15P (92% identical), RNU6-19P (92% identical), RNU6-949P (92% identical), RNU6-12P (91% identical), RNU6-13P (91% identical), RNU6-166P (91% identical), RNU6-31P (91% identical), RNU6-32P (91% identical), RNU6-33P (91% identical), RNU6-41P (91% identical), and 1287 more.